EPHB6 (EPH receptor B6)
Diseases named in the same sentence as EPHB6 in open-access papers (continued):
Sharing a sentence is not in itself a finding about the gene and the disease.
prostate carcinoma (4 papers, 2015 to 2023). A carcinoma that arises from epithelial cells of the prostate gland. "This provides new insight for the use of EphB6 RTK as a potential diagnostic/prognostic marker for prostate cancer." (PMID 25789021, 2015). "In the present study, the expression of EphB6 receptor in normal and prostate cancer tissue, and the association between EphB6 expression, clinicopathological findings and progression of prostate cancer was investigated." (PMID 25789021, 2015). "Additionally, the regulation of EphB6 expression by promoter methylation may be associated with altered expression in aggressive prostate cancer cell lines." (PMID 25789021, 2015). "The association between EphB6 expression, clinicopathological findings, proliferating-cell nuclear antigen (PCNA; another prognostic marker) and progression of prostate cancer was analyzed." (PMID 25789021, 2015). "The effect of EphB6 expression on biochemical progression-free (PSA-free) survival in prostate cancer patients was evaluated." (PMID 25789021, 2015). "Moreover, enzalutamide, a widely applied anti-androgen therapy in advanced prostate cancer, has been found to suppress EPHB6 expression by binding to the androgen-response-element on the EPHB6 promoter to stimulate tumor cell metastasis." (PMID 37637034, 2023). "The EphB6 has also been studied in thyroid-, and prostate cancer." (PMID 29299148, 2017). "Additionally, the potential association between the expression of EphB6 and proliferating-cell nuclear antigen (PCNA), an independent postoperative prognostic marker for prostate cancer patients, was assessed." (PMID 25789021, 2015). "In addition, significantly reduced EphB6 expression was observed within adjacent prostate cancer tissue in a considerable proportion of cases (Wilcoxon’s signed rank test, P<0.0001)." (PMID 25789021, 2015). "Additionally, data from the current study suggested that EphB6 expression is gradually and significantly reduced during the progression of prostate cancer from a low volume to a high volume, or from pT2 stage to pT3." (PMID 25789021, 2015). "Compared with corresponding normal tissue within the same patient, prostate cancer cells showed a significantly decreased expression level of EphB6 in 26 cases and retained a similar expression level in the remaining cases (Wilcoxon signed rank test, P<0.0001)." (PMID 25789021, 2015). "However, the reports with regard to the role of Eph RTK members, particularly EphB6, in prostate cancer, are insufficient." (PMID 25789021, 2015). "In conclusion, although several members of the Eph family are associated with the progression of cancer, the results of the present study indicated that EphB6 may have a tumor suppressor effect in prostate cancer, at least during early stages of this disease." (PMID 25789021, 2015). "This is consistent with previous semi-quantitative RT-PCR studies on prostate cancer cell lines, which showed downregulation of EphB6 mRNA in a cell line derived from primary prostate cancer tissue, compared with that in a cell line derived from normal prostatic tissue from the same patient." (PMID 25789021, 2015). "In prostate cancer tissue, EphB6 expression was detected in the majority of cases (97.8%)." (PMID 25789021, 2015). "This study revealed that EphB6 may have a tumor suppressor effect in prostate cancer, at least during early stages of this disease." (PMID 25789021, 2015). "The expression of EphB6 was evaluated in normal and prostate cancer tissues from each patient." (PMID 25789021, 2015). "Within the limits of the investigated cases, the results indicate that EphB6 RTK has no proliferation-stimulating effect in prostate cancer." (PMID 25789021, 2015).
colorectal tumors (3 papers, 2016 to 2017). "EphB6 overexpression together with APC gene mutations was suggested to promote the development of colorectal tumors." (PMID 29299148, 2017). "EphB6 overexpression together with Apc mutation leads to the development of colorectal tumors in vivo." (PMID 27145271, 2016). "However, we report here for the first time that the loss of EPHB6 contributes to the metastatic spread of colorectal tumors." (PMID 28262839, 2017). "Here, we have investigated the importance of the loss of EPHB6 during intestinal tumorigenesis using isogenic in vitro systems, different mouse models and annotated collections of primary colorectal tumors, and found that the loss of EPHB6 contributes to the metastatic spread of colorectal tumors." (PMID 28262839, 2017). "Collectively, these results demonstrate for the first time a role for EPHB6 in the metastatic spread of colorectal tumors." (PMID 28262839, 2017). "In this study we used isogenic in vitro systems, animal models and large collections of primary colorectal tumor samples to investigate the functional relevance of EPHB6 during colorectal tumorigenesis." (PMID 28262839, 2017). "Significant variability was observed in the levels of expression of EPHB6 in colorectal tumors." (PMID 28262839, 2017). "However, significantly lower levels of EPHB6 expression were observed in lymph node metastasis compared to primary colorectal tumors." (PMID 28262839, 2017).
glioma (3 papers, 2012 to 2024). A benign or malignant brain and spinal cord tumor that arises from glial cells (astrocytes, oligodendrocytes, ependymal cells). "In the RMPAlow gliomas, a different set of RTK signaling-related genes including MET (8.9%), EPHA1 (8.9%), EPHB6 (8.9%), EPHB4 (8.3%), BRAF (8.9%), FGF6 (11.9%), FGF23 (11.9%), NTF3 (11.9%), and ANGPT1 (9.5%) were amplified." (PMID 27385209, 2016).
ovarian carcinoma (3 papers, 2012 to 2021). A malignant neoplasm originating from the surface ovarian epithelium. "Metabolic abnormalities of EPHB6 promote cancer development and progression, which was proven in invasive melanoma and prostate, gastric, and ovarian cancers." (PMID 34676211, 2021).
triple-negative breast carcinoma (3 papers, 2016 to 2021). An invasive breast carcinoma which is negative for expression of estrogen receptor (ER), progesterone receptor (PR), and human epidermal growth factor receptor 2 (HER2). "In our work, we used a genome-wide SL screen combined with expression and interaction network analyses, and identified the SRC kinase as a SL partner of EPHB6 in triple-negative breast cancer (TNBC) cells." (PMID 27418135, 2016).
Alzheimer disease (2 papers, 2024). A progressive, neurodegenerative disease characterized by loss of function and death of nerve cells in several areas of the brain leading to loss of cognitive function such as memory and language. "In addition, altered alternatively splicing of the EPHB6 gene (located on chromosome 7q34 in the vicinity of the EPHA1 gene) has been associated with Alzheimer’s disease risk and a rare autosomal EPHA6 copy number gain was found to co-segregate with familial Alzheimer’s disease status." (PMID 39706267, 2024). "EPHB6 levels in cerebrospinal fluid were found to correlate with the levels of Tau and phosphorylated Tau, two biomarkers of Alzheimer’s disease pathology." (PMID 39706267, 2024). "In both cases, the specific mechanisms by which TAS2R41 and TAS2R60 influence the expression or function of EPHB6 and ADGRB3 in the context of Alzheimer's disease remain to be fully elucidated." (PMID 39284855, 2024).
autism (2 papers, 2020 to 2023). Persistent deficits in social interaction and communication and interaction as well as a markedly restricted repertoire of activity and interest as well as repetitive patterns of behavior. "Abnormal arrangement of neural cell bodies is observed in neurodevelopmental diseases such as autism, for which EPHB6 is a risk gene." (PMID 37149633, 2023). "In short, these results indicated that dysregulated gut microbiota and vitamin B6 defect led to autism-like behavior via the D1R-mediated pathway in EphB6-deficient mice." (PMID 32819434, 2020). "In summary, our study uncovers a key role for the gut microbiota in the autism-like behavior of EphB6-deficient mice." (PMID 32819434, 2020). "Second, we found that gut microbial dysbiosis is required for autism-like behavior in EphB6-deficient mice." (PMID 32819434, 2020). "Mechanistically, gut microbiota-mediated defects in vitamin B6 regulate autism-like social behavior by decreasing the dopamine levels and inducing E/I imbalance in the mPFC of EphB6-deficient mice." (PMID 32819434, 2020). "Third, we found that defect of vitamin B6 is crucial for the gut microbiota-mediated autism-like behavior in EphB6-deficient mice." (PMID 32819434, 2020). "In 1998, two-stage genome research on susceptibility loci in autism found transcripts mapped to the chromosome 7q region that are associated with a predisposition to autism, including EPHB6." (PMID 32819434, 2020). "Because the abnormal behaviors were likely due to brain-related problems, we attempted to determine how the gut microbiota affected the brain and subsequently caused autism-like behavior in EphB6-deficient mice." (PMID 32819434, 2020). "Our study uncovers a key role for the gut microbiota in the regulation of autism-like social behavior by vitamin B6, dopamine, and the E/I balance in EphB6-deficient mice, and these findings suggest new strategies for understanding and treating ASD." (PMID 32819434, 2020). "In addition, transcriptomic sequencing found that EPHB6 is a risk gene for autism, and that EphB6 expression was elevated in whole blood genomic profiling tests of autistic patients." (PMID 37149633, 2023). "More importantly, transplantation of the fecal microbiota from EphB6-deficient mice resulted in autism-like behavior in antibiotic-treated C57BL/6J mice, and transplantation of the fecal microbiota from wild-type mice ameliorated the autism-like behavior in EphB6-deficient mice." (PMID 32819434, 2020). "To determine whether the decrease in dopamine contributed to the autism-like behavior of EphB6-deficient mice and considering the fast metabolism of dopamine in the brain, we injected agonists of dopamine receptors into the mPFC of mice." (PMID 32819434, 2020). "Here, using our transgenic mouse models, we found that the deletion of EphB6 in mice induced autism-like behavior that mimicked the core symptoms of ASD patients fairly well." (PMID 32819434, 2020). "Here, we found that the deletion of EphB6 induced autism-like behavior and disturbed the gut microbiota in mice." (PMID 32819434, 2020). "First, we attempted to identify the key region of the brain affected by the dysregulated gut microbiota in mice with deletion of EphB6 and that was responsible for the resulting autism-like behavior." (PMID 32819434, 2020). "Collectively, the results showed that the deletion of EphB6 in mice resulted in autism-like behavior, including stereotyped behavior and social deficits, accompanied by anxiety-like behavior, but did not result in any evidence of intellectual disability." (PMID 32819434, 2020). "In our study, we found that EphB6 is functionally associated with ASD and regulates autism-like social behavior by gut microbiota-mediated vitamin B6 and dopamine." (PMID 32819434, 2020). "In addition, genomic studies have suggested that EphB6 is a candidate autistic spectrum disorder (ASD)-associated gene, and autism-like behavior is observed in EphB6-deficient mice." (PMID 37149633, 2023).
autism (continued). "Therefore, to study the relationship between gut microbial dysbiosis and autism-like behavior in mice with deletion of EphB6, we gavaged the fecal microbiota from 8-week-old male WT or KO mice to 3-week-old SPF male C57BL/6J mice for 1 week." (PMID 32819434, 2020).
breast tumor (2 papers, 2018 to 2024). "The application of methylation-dependent regulation of EphB6 expression is further evident in an investigation utilizing MSP (methylation-specific polymerase chain reaction) for potential detection of breast tumor cells in circulation." (PMID 29682554, 2018). "Upon phosphorylation, EphB6 interacts with c-Cbl to promote breast tumor cell motility." (PMID 29682554, 2018).
colorectal adenocarcinoma (2 papers, 2016 to 2024). The most common type of colorectal carcinoma. "EPHB6 is an ephrin-B receptor, where its overexpression promotes CRC and modulates the tumor immune microenvironment of primary colorectal adenocarcinomas metastasizing to the liver or lungs." (PMID 39408697, 2024).
lymph node metastases (2 papers, 2016 to 2025). "High EphB6 expression was significantly associated with advanced tumor staging and lymph node metastasis, as well as poorer patient outcomes, leading to higher mortality rates." (PMID 40421081, 2025). "This study demonstrated that high EphB6 expression was significantly associated with advanced tumor staging and lymph node metastasis, as well as poorer patient outcomes, leading to higher mortality rates." (PMID 40421081, 2025). "Enhanced EphB6 expression was significantly associated with larger tumor size, the presence of lymph node metastases, the presence of capsular, lymphatic and vascular invasion and increased risk of recurrence." (PMID 27058903, 2016).
thymoma (2 papers, 2021 to 2023). A neoplasm arising from the epithelial cells of the thymus. "In our study, the more indolent thymoma subtypes (types A and AB) were also associated with higher lymphocytic EphB6 expression in contrast with thymic cancer, which showed no expression (p < 0.001)." (PMID 34943502, 2021).
acute lymphoblastic leukemia (1 paper, 2021). Leukemia with an acute onset, characterized by the presence of lymphoblasts in the bone marrow and the peripheral blood. "On the contrary, El Zawily and colleagues showed that EphB6 and Akt are functionally negatively correlated in doxorubicin-sensitivity of pediatric T cell acute lymphoblastic leukemia cells." (PMID 33802447, 2021).
acute myeloid leukemia (1 paper, 2021). Acute myeloid leukemia (AML) is a group of neoplasms arising from precursor cells committed to the myeloid cell-line differentiation. "It has been reported that EPHB6 is over-expressed in acute myeloid leukemia." (PMID 34072627, 2021).
age-related macular degeneration (1 paper, 2021). Age-related loss of vision in the central portion of the retina (macula), secondary to retinal degeneration. "WEE1, SMC2, HMGB1, RRM2, and POLA1 proteins were also observed to be involved in the progression and invasion of retinoblastoma; SLC24A2 and DTX4 in age-related macular degeneration; and EPHB6, EFNB3, and SHC1 in glaucoma." (PMID 34646884, 2021).
atherosclerosis (1 paper, 2024). A disease characterized by the build-up of fatty material and calcium deposition in the arterial wall resulting in partial or complete occlusion of the arterial lumen. "EPHB6 encodes the receptor tyrosine kinase that was proved to regulate the vascular smooth muscle cell contraction and endothelial cell, and contribute to the development of atherosclerosis." (PMID 39054468, 2024).
colorectal adenoma (1 paper, 2016). An adenoma that arises from the colon or rectum. "In our study, we showed that endogenous EphB6 was upregulated in human colorectal adenomas and adenocarcinomas compared with normal tissues." (PMID 27145271, 2016).
glioblastoma (1 paper, 2023). The most malignant astrocytic tumor (WHO grade IV). "The results revealed that EphA2, EphB2, EphB3, and EphB4 were significantly upregulated, while EphA4 and EphB6 were significantly downregulated in glioblastoma than normal brain tissues, respectively." (PMID 37146061, 2023).
intestinal tumor (1 paper, 2017). "Importantly, no changes in the incidence of spontaneous intestinal tumors were observed in EphB6−/− mice at 21 months of age when compared to EphB6+/+ animals, indicating that the loss of EphB6 does not efficiently initiate tumor formation." (PMID 28262839, 2017). "Collectively, these results demonstrate that EPHB6 does not regulate the proliferation of intestinal epithelial cells either in the normal mucosa or in primary intestinal tumors." (PMID 28262839, 2017).
Kabuki syndrome (1 paper, 2022). Kabuki syndrome (KS) is a multiple congenital anomaly syndrome characterized by typical facial features, skeletal anomalies, mild to moderate intellectual disability and postnatal growth deficiency. "Some of the downregulated genes in KO clones are associated with regulation of T-cell activation (e.g. Ephb6) and neuron projection development (e.g. Tnik), consistent with autoimmune disorders and neurological issues in Kabuki syndrome." (PMID 35871105, 2022).
liver cancer (1 paper, 2019). An epithelial or non-epithelial malignant neoplasm that arises from the liver. "Experimental data confirmed that the EPHB6 mutation induces paclitaxel resistance in various cancer types, including lung, skin, and liver cancers." (PMID 31160603, 2019).
lung adenocarcinoma (1 paper, 2020). A carcinoma that arises from the lung and is characterized by the presence of malignant glandular epithelial cells. "Importantly, CLDN1 expression was downregulated and correlated with the downregulated expression of EPHB6 in stage IV lung adenocarcinoma, suggesting that CLDN1 may correlate with EPHB6 expression and be a metastasis suppressor." (PMID 32754286, 2020).
metastatic cancers (1 paper, 2024). A carcinoma which has spread from the original site of growth to another anatomic site. "EphB6 is an understudied ephrin receptor tyrosine pseudokinase that is downregulated in multiple types of metastatic cancers." (PMID 38627519, 2024).
Ovarian cyst (1 paper, 2006). The presence of one or more cysts of the ovary. "Hence EphA1, EphA2, EphB2, EphB3, EphB6, ephrin A1, ephrin A5 and ephrin B1 were selected for further analysis in an additional fourteen tumor samples, one ovarian cyst and one ovarian adenoma." (PMID 16737551, 2006).
ovarian serous carcinoma (1 paper, 2016). "Decreased expression of EphB6 was found in ovarian serous carcinomas compared with that in normal fallopian tubes." (PMID 27887627, 2016). "Previously, we detected the EphB6 protein in ovarian serous carcinoma." (PMID 27887627, 2016).
pancreatic cancer (1 paper, 2021). "Specifically, we identified three RTKs, MET, EPHB6, and RYK, which are associated with a poor prognosis regardless of the immune status in patients with pancreatic cancer." (PMID 34479614, 2021).
pituitary tumor (1 paper, 2024). A benign or malignant neoplasm affecting the pituitary gland. "Human normal pituitaries and pituitary tumors were examined for EphB6 mRNA expression using real-time PCR and for EphB6 protein by immunohistochemistry and Western blotting." (PMID 38341842, 2024). "The aim of this study was to assess the expression of EphB6 in pituitary tumors." (PMID 38341842, 2024).
spina bifida (1 paper, 2022). A congenital neural tube defect in which vertebrae are not fully formed. "Likewise, in the exome dataset of proband SB5A with EPHB6 variant (rs780569137), five variants in spina bifida-related genes were likely pathogenic based on MAF and in silico predictions." (PMID 35741713, 2022). "We reported that three out of seven spina bifida probands and three out of thirteen family members carried a variant in either EPHA2 (rs147977279), EPHB6 (rs780569137) or EFNB1 (rs772228172)." (PMID 35741713, 2022). "There were no shared exonic variants in any known mammalian Eph and ephrin genes (EPHA1–EPHA8, EPHA10, EPHB1–EPHB4, EPHB6, EFNA1–EFNA5, and EFNB1–EFNB3) that fulfilled the MAF < 0.01 criteria in all seven spina bifida probands." (PMID 35741713, 2022).
spina bifida aperta (1 paper, 2022). "The rs780569137 variant in EphB-type receptor EPHB6 is an A to G base change at 142,562,247 on chromosome 7, in an individual with spina bifida aperta, SB5A." (PMID 35741713, 2022).
thymic epithelial tumors (1 paper, 2021). "In view of above considerations, the present study aimed to assess immunohistochemical EphA1, EphA2, EphA4, EphA6, EphB1, EphB2, EphB4 and EphB6 expression in 98 thymic epithelial tumors in association with clinicopathological parameters and patients’ survival." (PMID 34943502, 2021).